IL1B (interleukin 1 beta)
Diseases named in the same sentence as IL1B in open-access papers (continued):
Sharing a sentence is not in itself a finding about the gene and the disease.
tumor (continued). "In TAMs-tumor cells in vitro co-culture model, tumor necrosis factor-related apoptosis-inducing ligand (TRAIL) reprograms TAMs to M1-like phenotype by inducing expression of proinflammatory cytokines like IL1B, IL6, TNFα." (PMID 32219066, 2020). "It is regulated by endotoxin and some cytokines including TNF-α, IL-1β, and IFN-γ in vitro and in vivo; ICAM-1 plays an important role in promoting adhesion at the site of inflammation, controlling tumor progression and metastasis, and regulating immune responses in the body." (PMID 32089647, 2020). "A recent study demonstrated that IL-1β-polarized Th17 cells are effector cells against tumors, whereas TGF-β-polarized Th17 cells do not have such a potent antitumor effect, which was attributed to the induction of CD73 by TGF-β to support tumor growth." (PMID 32604872, 2020). "Although IL-1β is found to promote inflammation in non-tumor diseases, there is little evidence that elucidates the role of IL-1β in tumors or TME." (PMID 32346605, 2020). "Ghrelin did not prevent tumor-induced increases in circulating inflammatory cytokines or in BAT IL-1β or MCP-1 protein levels." (PMID 32934774, 2020). "Moreover, increased stability of HIF-1α in hypoxic conditions in HCC increases the secretion of IL-1β and promotes EMT and metastasis of tumor cells." (PMID 32770081, 2020). "In addition, the cytokines IL-1α, IL-1β, IL-6, IL-17A, and TNF-α promote tumor initiation, progression, angiogenesis, and metastasis in many human malignancies, including CRC, and our findings are consistent with previous studies." (PMID 33488574, 2020). "Conditioned medium from high EGFR-expressing tumor cells treated with NB-PDT led to the maturation of human dendritic cells, as indicated by the upregulation of CD86 and MHC II on their cell surface, and the increased release of IL-12p40 and IL-1β." (PMID 32326519, 2020). "Surprisingly, treatment with either the anti-IL-1β antibodies or the IL-18 binding protein (BP) or both did not affect the rate of tumor growth." (PMID 33042810, 2020). "IL-18 inhibition, and the combination of both IL-1β and IL-18 inhibition also had no impact on tumor cell growth." (PMID 33042810, 2020). "Furthermore, ID1 knockdown reversed up-regulation of stem cell related markers induced by IL-1β stimulation in SCC7 cells (P < 0.05) and B16-F10 tumor cells (P < 0.05)." (PMID 32547321, 2020). "However, released by the TAMs in the TME, IL-1β has an opposite role, supporting EMT, tumor growth and anti-apoptosis." (PMID 33228048, 2020). "In this line, a recent study demonstrated high expression of cachexia-inducing factors, such as CXCL8, IL6, IL1B, CCL2, and TNF, in pancreatic cancer patients, whose tumor was classified as of low-purity (higher proportion of immune cells than of malignant cells)." (PMID 33604297, 2020). "Besides, another study indicated that HMGB1 synergizes with ATP to induce IL‐1β release by DCs and that antibody specific for HMGB1 abrogated the ability of DCs to produce IL‐1β in contact with dying tumor cells." (PMID 33179413, 2020). "We found that, when the NLRP3 inflammasome is activated, two groups of tumor cells could be identified based on LDH release and IL1β secretion." (PMID 33613529, 2020). "Purified ILCs from non-affected colon, tumor border and central tumor tissue were cultured in the presence of IL-2 plus IL-1β and IL-18 for 7−9 days and the resulting expression of HLA-DR and T-cell co-stimulatory molecules was assessed." (PMID 32341343, 2020). "For example, Smad7 retains the NF-κB inhibitor alpha (IκBα) expression; inhibits NF-κB-activated genes such as tumour necrosis factor alpha (TNFα), interleukin 1 beta (IL1β), and intercellular adhesion molecule 1 (ICAM1); and thereafter plays an anti-inflammatory role in several tumour cell lines." (PMID 33282009, 2020).
tumor (continued). "Cross-linking and tumour antigen-specific IgE antibody-dependent cellular cytotoxicity (ADCC) of cancer cells by cancer patient-derived monocytes triggered release of pro-inflammatory mediators (TNFα, MCP-1, IL-10, CXCL-10, IL-1β, IL-6, IL-23)." (PMID 33203088, 2020). "IL-1β, TNF-α, and certain chemokines promote inflammation in non-tumor diseases." (PMID 32346605, 2020). "In our previous study, RT-R-MDA-MB-231 cells released higher levels of IL-1β, which is secreted by inflammasome activation, than MDA-MB-231 cells, and IL-1β was related to tumor progression in MDA-MB-231 and RT-R-MDA-MB-231 cells, suggesting its involvement in tumor aggressiveness." (PMID 32397236, 2020). "In support of IL-10 tumor suppressor action, several studies observed that IL-10 was able to induce AML blasts apoptosis in vitro probably through the inhibition of proinflammatory cytokines production, such as IL-1α, IL-1β, IL-6, GM-CSF and TNF-α." (PMID 32443460, 2020). "IL-1β and IL-23 increased percent of IL-22-producing ILC3 in tumor tissue." (PMID 32649314, 2020). "In addition, the DCs supplied with the supernatant from M1-infected tumor cells produced much higher concentrations of IL-12, TNF-α, and IL-1β." (PMID 33311488, 2020). "However, as other cytokines, not necessarily a product of inflammasome activity, are left unchecked by IL-1β or CCL5 inhibition, MDSC recruitment and tumor metastasis would be unaffected in the long run." (PMID 31685946, 2020). "AA tumor samples present significant fold-change elevation in gene expression compared with CA for Interleukin 8 (IL8), forkhead box P3 (FOXP3), and Interleukin 1 beta (IL1B) genes." (PMID 33425763, 2020). "In this latter context, a recent report has demonstrated that IL-4 and IL-1β act synergistically in the absence of TGF-β to empower a tumor-specific TH9 response, which mediates robust antitumor activity." (PMID 33584721, 2020). "Besides phenotypic maturation, further activation of moDCs was investigated by measuring their release of IL-12, IL-1β, and IL-10 after incubation with NB-PDT treated tumor supernatant." (PMID 32326519, 2020). "IL-1β is known to influence apoptosis of tumor cells via induction of STAT3 Concordantly, we found a tendency towards up-regulation of STAT3 and decreased apoptosis rates in GBM cells after IL-1β treatment." (PMID 32069807, 2020). "TAMs participate in the tumour angiogenesis by secreting pro‐angiogenic factors, including VEGF‐A, EGF, PlGF, TGF‐β, TNF‐α, IL‐1β, IL‐8, CCL2, CXCL8 and CXCL12, and enable tumour metastasis by up‐regulated N‐cadherin and Snail, whereas down‐regulated E‐cadherin." (PMID 32588948, 2020). "IL‐1β secreted from GBC cells played a central role in the cell extravasation to the liver, as IL‐1β induced endothelial cell apoptosis and permeability, giving rise to cellular fenestration favorable for tumor cell extravasation." (PMID 33252861, 2020). "Inflammation in the tumor microenvironment and production of inflammatory cytokines such as TNF-α, IL-1β, and IFNγ (that could also be induced by HCMV) may lead to further induction of PRLR." (PMID 32121009, 2020). "In vitro bioactivity tests showed that HPP has significant immune activity and may alter the tumor microenvironment by regulating the secretion of the inflammatory cytokines NO, IL-6, RANTES, IL-23, and IL-1β." (PMID 32850623, 2020). "IL-1β derived from TAMs suppresses the expression of 15-hydroxyprostaglandin dehydrogenase (15-PGDH), an enzyme involved in prostaglandin degradation in PDAC cells, which results in tumor growth and poor prognosis for PDAC patients." (PMID 32635472, 2020). "Furthermore, the cytokines related to tumor growth, EMT, metastasis and drug resistance, such as IL-1B, IL-2, Il-4, IL-6, IL-10, IL-17, KC (GRO), were mainly expressed in mT obese models." (PMID 32411709, 2020).
tumor (continued). "Microglia are essential for tissue repair processes and the maintenance of homeostasis during infectious diseases, ischemic lesions, and tumor growth, which can activate the over-expression of proinflammatory cytokines, e.g., TNF-α, IL-1β as well as neurotoxic radicals, e.g., ROS, nitric oxide." (PMID 33628177, 2020). "The aim of the present study was to measure the tumor TNF-alpha, interleukin-1 beta (IL-1 beta), adiponectin, and adropin levels that play a role in systemic inflammation in OSAS patients for determining whether they are related to OSAS or not." (PMID 32454912, 2020). "In this study, inflammatory cytokines that could enhance the tumourigenic process such as IL-6, IL-1β, and TNF-α were decreased in FLP-treated MO mice in the tumour tissues and serum compared to those of MO mice, which is in accordance with previous studies." (PMID 32308722, 2020). "They indicated that the cytokines secreted by these cells (IL-1β, Il-6, IL-8, IL-23 and TGF-β) could explain the high infiltration of Th17 cells at tumor site." (PMID 32121394, 2020). "As inhibiting IL-1β had limited efficacy as a therapeutic for metastatic expansion in the longer term, the steps of subsequent tumor expansion seem to be independent of stromal pyroptotic cascade initiated by PI." (PMID 31685946, 2020). "IL-1β and IL-23 increased levels of IL-22 mRNA and IL-22-producing ILC3 in 4T1 tumor." (PMID 32649314, 2020). "We showed IL-1β and IL-23 did not directly increase cell proliferation in cell culture, but rather increased tumor size in the transplant model in vivo." (PMID 32649314, 2020). "Furthermore, HTiO2 nanoparticle-based SDT upregulated the levels of pro-inflammatory cytokines such as interleukin (IL)-1β, IL-6, and tumor necrosis factor (TNF)-α within the tumor, increasing the immune response against the tumor." (PMID 33505987, 2020). "In our data, Mø_c1 represented the most abundant macrophages (37.10%) with high expression of IL1B, as well as CXCL10 and CXCL9, which might be involved in anti-tumor responses." (PMID 33298893, 2020). "Others have described modulation of cytokine production of IL-1α, IL-1β, IL-2, IL-4, IL-6, IL-8, IL-10, IL-17A, TNF-α, and IFN-γ on tumor cells treated with conventional PDT, but their increase or decrease seems to highly depend on the cell line and PDT protocol used." (PMID 32326519, 2020). "Although IL-1β, IL-6, and TNF-α have been shown to be regulated by MK2 signaling, cytokines often act in autocrine or paracrine manners to regulate production of other cytokines in the tumor microenvironment." (PMID 32216812, 2020). "Additionally, IL‐1β release from dendritic cells was shown to be essential for priming of interferon gamma (IFNγ)‐producing CD8+ T cells and elimination of tumor cells." (PMID 32770571, 2020). "Specifically, IL-1β can promote AML blasts proliferation and survival, through the generation of a pro-inflammatory BM microenvironment, enhancing the production of other pro-leukemic chemokines and disrupting the anti-tumor immune response." (PMID 32443460, 2020). "Higher IL-1β levels can induce myeloid-derived suppressor cells (MDSC), which exhibit phenotypic similarity to anti-inflammatory M2 macrophages capable of suppressing anti-tumour immunity, and resulting in tumour growth." (PMID 32168834, 2020). "In addition, we recently observed that caspase-8 expression in GBM played a non-canonical function sustaining NF-κB activation, cytokine production (i.e., IL-6, IL-8, IL-1β, MCP-1, and VEGF-α), and tumor growth in vivo." (PMID 32545574, 2020). "Taken together, the fact that SOCS2 is frequently deregulated in IL-1β-related cancers indicates that SOCS2 expression and its regulatory functions in DCs may support cancer progression by dampening anti-tumor immune responses." (PMID 31775389, 2019).
tumor (continued). "Our data describe a paracrine signaling mechanism between ER+BCCs, NAFs, and TAFs that result in the secretion of IL1β from fibroblasts without requirement for immune cell response, leading to tumor cell proliferation." (PMID 31419632, 2019). "Importantly, in addition to promoting tumour growth at the primary tumour site, we found that depletion of CAF-derived IL-1β resulted in inhibition of lung metastasis." (PMID 31558756, 2019). "Pulsing BMCs with DRibbles increased the in vitro production of pro-inflammatory cytokines IL-6, IL-1β, IL-12 and Type I IFNs and replacing DR-pulsed-BMCs with DRibbles also delayed tumor growth kinetics, albeit not as prominently." (PMID 31747946, 2019). "The influence of CAFs is effected through a paracrine function by means of the secretion of growth factors and cytokines, such as IL-1β, IL-6, IL-8, SDF-1, and NFκB, in order to induce immune cell recruitment that may contribute to tumor progression." (PMID 31086100, 2019). "IL-1β activates endothelial cells to produce vascular endothelial growth factor (VEGF) and other proangiogenic factors (e.g., TNF) which provide an inflammatory microenvironment for angiogenesis and tumor progression." (PMID 30642137, 2019). "Whilst these are essential to study metastasis of human tumour cells in vivo, they do not give us any insight into the interplay between IL1β-Wnt inhibition and the immune system during metastatic colonisation." (PMID 31676788, 2019). "M1 macrophages act in microbiocidal and anti-tumor activity with the secretion of IL1β, IL12 and TNF-α, whereas M2 macrophages act in tissue remodeling, immune tolerance and tumor progression with the secretion of IL4, IL10 and transforming growth factor (TGF)-β." (PMID 31408948, 2019). "In addition, IR-induced inflammatory cytokines—IL-1β, tumor necrosis factor (TNF)-α, and type I and II IFNs—affect the upregulation of vascular cell adhesion molecule 1 (VCAM-1) on tumor endothelium." (PMID 31261963, 2019). "In turn, mice bearing non-metastatic 67NR tumors showed low expression levels of G-CSF and IL-1β in the tumor mass as well as no elevation in neutrophil counts or NETosis markers." (PMID 31552036, 2019). "Moreover, CAF-derived inflammasome signalling facilitated tumour growth and metastasis, which was attenuated when NLRP3 or IL-1β were specifically ablated." (PMID 31558756, 2019). "COX-2 is not expressed in the non-pathological colonic mucosa, while it is induced in the tumor microenvironment by pro-inflammatory stimuli such as bacterial lipopolysaccharides, IL-1β, IFN-γ and TNF-α." (PMID 31027294, 2019). "High concentrations of IL-1β activate CD8+ T cells, which promotes anti-tumor effects." (PMID 31754923, 2019). "Conversely, expression of IL-1β by MDSCs in response to either gemcitabine or 5-FU was demonstrated to induce IL-17 expression by CD4+ T cells, which suppressed the chemotherapy-dependent control of tumor growth." (PMID 31379850, 2019). "d Tumor cell- and TAM-derived IL-1α and IL-1β, respectively, induce TSLP secretion by CAFs." (PMID 30760333, 2019). "Similarly, in tumor tissues of CMS-induced mice, the expression and phosphorylation of ABL1, p-NF-κB1, p-STAT3, IL-6, IL-1β, and COX2 significantly increased." (PMID 31396300, 2019). "MDSC (CD11b+ Gr-1+) are cells that highly express NLRP3 and pro-IL-1β mRNA, compared to their counterpart Gr-1 negative cells purified from spleen of CT-26 tumor-bearing mice." (PMID 31217433, 2019). "SI-CLP was shown to induce the secretion of IL-1β, IL-6, IL-12, and IL-13 in PMA-treated THP-1 cells, suggesting that it may serve as a regulator of inflammation and in the tumor microenvironment." (PMID 32038607, 2019). "Enhanced production of PGE2, IL-1β, IL-6, TGF-β as well as arginase, indoleamine 2,3-dioxygenase (IDO) and IL-10 from MDSCs implicitly mediate reciprocal differentiation of Th17 and Treg cells in a defined circumstance of tumor microenvironment." (PMID 31024835, 2019).
tumor (continued). "Case 1, showing significant intra-tumoral IL-1β, was the only case that had a diagnosis of distant metastasis and late-stage cancer; cases 3 and 7, diagnosed with late-stage RCC tumor, had none and trace (+) amount of IL-1β, respectively." (PMID 31816951, 2019). "In addition, we have identified IL1β and CDH1 expression by tumor cells as predictive markers for this interaction." (PMID 30993013, 2019). "Furthermore, our study showed a weak correlation between IL-1β/pro- IL-1β ratio, as a degree of IL-1β activation, and the level of GSTO1 expression in ccRCC tumor tissue." (PMID 31861116, 2019). "The impact of blocking IL1β and PDGF-BB signaling on tumor growth in vivo was rather modest." (PMID 31419632, 2019). "Finally, it was confirmed that the bioactive compounds of compound Liuju formula have not only a killing effect on NSCLC tumor cells but also a synergistic effect on inhibiting the secretion of correlative inflammatory mediators, including TNF-α and IL-1β." (PMID 31949474, 2019). "Various tumor-derived factors have been reported to induce immature myeloid cells (CD33+ cells) to differentiate to MDSCs, these factors include prostaglandin E2, IL-6, IL-10, IL-1β, TGF-β, and proangiogenic factors such as vascular endothelial growth factor." (PMID 31620141, 2019). "Interestingly, commonly downregulated genes included c-Myc and c-Myc target genes, as well as additional pro-oncogenic factors, such as IL1B, NT5E (CD73), and other molecules with functions in tumor immune escape 38,39, which were validated by qPCR." (PMID 31554806, 2019). "This study identifies dual functions for caspase-11 during CAC—generating IL-1β via the non-canonical inflammasome; and mediating the tumour suppressor activities of STAT1." (PMID 30538296, 2019). "ATP is involved in the recruitment of monocytes to the tumor (via the P2Y2 receptor) and participates in the production of interleukin (IL)-1β (through the P2RX7 receptor present on DCs and the activation of inflammasome NLRP3) necessary for the activation of T cells." (PMID 31261963, 2019). "Luminex analysis of cytokine or growth factor expression in tumour lysates from AsPC‐1 PDAC peritoneal dissemination xenografts demonstrated NPT+Gem therapy‐induced changes in most studied marker proteins including IP‐10, MDC, PAI‐1, MIP‐1b, IL‐1B and GM‐CSF." (PMID 30941918, 2019). "Strikingly, the expression of adhesion molecules on lung ECs isolated from tumour-bearing mice was also attenuated in mice injected with Il1b−/− fibroblasts, suggesting that CAF-derived IL-1β has systemic effects that may support metastasis." (PMID 31558756, 2019). "Nevertheless, NLRP3 and pro-IL-1β mRNA expression is not changed in CD11b+ Gr-1+ obtained from tumor-free (naive) or CT-26 tumor-bearing mice." (PMID 31217433, 2019). "They found that the application of dinitrofluorobenzene (DNFB) activated IL-1β in the mouse skin and recombinant IL-1β could partially replace DNFB treatment as an enabler of tumor growth in their model." (PMID 31139332, 2019). "Furthermore, when tumour-bearing DCs were co-cultured with cryo-thermal eosinophils, the expression level of pro-inflammatory cytokines (CXCL10, IL-1β, IL-15 and IL-6) was increased as compared to tumour-bearing DCs co-cultured with tumour-bearing eosinophils." (PMID 31519961, 2019). "Acid-induced NF-κB activation downstream promotes the secretion of several cytokines, chemokines, and growth factors (IL1a, IL1b, IL6, IL8, IL23a, CCL5, CCL7, CXCL2, GM-CSF, and G-CSF) that can elicit local cancer aggressiveness, tumor immune escape, and tumor-induced nociception and hyperalgesia." (PMID 30825056, 2019). "Therapeutic targeting of the IL-1β/IL-1R or the CXCL1/CXCR2 circuits in an adjuvant setting circumvents chemotherapy resistance in breast cancer patients, and the pre-clinical model of IRISOE TNBC tumor." (PMID 31014367, 2019).